CDCA5 (cell division cycle associated 5)
Diseases named in the same sentence as CDCA5 in open-access papers (continued):
Sharing a sentence is not in itself a finding about the gene and the disease.
hepatocellular carcinoma (18 papers, 2018 to 2024). A malignant tumor that arises from hepatocytes. "Additionally, CDCA5 has been implicated in several tumor progressions, including bladder cancer, hepatocellular carcinoma, gastric cancer and esophageal squamous cell carcinoma." (PMID 38978058, 2024). "A twenty gene-based gene (including CDCA5) set variation score reflected the pathological progression from cirrhosis to hepatocellular carcinoma." (PMID 38890649, 2024). "The role of these genes (UBE2T, CDCA3, and CDCA5) in the progression of hepatitis, cirrhosis and hepatocellular carcinoma remains to be further investigated." (PMID 38890649, 2024). "Furthermore, the significant association with nodal status and high CDCA5 expression at both the mRNA and protein level indicates its ability to be involved in BC invasion and metastasis which was confirmed by the in vivo and in vitro models in hepatocellular carcinoma and in this study in BC." (PMID 36428736, 2022). "However, the prognostic value of CDCA5 and its underlying mechanism contributing to tumorigenesis in hepatocellular carcinoma (HCC) remain poorly understood." (PMID 32694239, 2020). "Multiple studies have revealed that CDCA5 is overexpressed in various cancers, such as lung cancer, oral squamous cell carcinoma, gastric cancer, pleural mesothelioma and hepatocellular carcinoma, and acts as a tumor promoter 15, 17-20." (PMID 32201512, 2020). "This study also confirmed that the inhibition of CDCA5 expression in hepatoma cells decreased the rate of proliferation and increased the rate of apoptosis as determined by colony formation assays and flow cytometry, which was consistent with previous studies." (PMID 30497429, 2018). "In hepatoma cell lines, CDCA5 expression was confirmed to increase cell viability and proliferation, while CDCA5 inhibition caused decreased rates of proliferation and apoptosis based on colony formation assays, flow cytometry, and nude mouse experiments." (PMID 30497429, 2018). "Additionally, silencing the CDCA5 gene has been shown to inhibit the AKT signaling pathway, activating the pro-apoptotic signaling pathway and revealing CDCA5’s functional role in hepatocellular carcinoma." (PMID 39273692, 2024). "Earlier research has also shown that CDCA5 might influence cell malignant behavior in prostate cancer, bladder cancer, and hepatocellular carcinoma through modulating PI3K/AKT/mTOR signaling." (PMID 37287817, 2023). "CDCA5 expression, which plays an essential role in the cell cycle, has been identified as an upregulated gene in various types of cancer, including breast, bladder, esophageal squamous cell carcinoma, colorectal and hepatocellular cancer." (PMID 36428736, 2022). "The upregulation of CDCA5 expression occurs in several types of cancer, including hepatocellular carcinoma, colorectal, oral squamous cell carcinoma, implying that it may act as an oncogene promoting tumor progression." (PMID 36428736, 2022). "Moreover, CDCA5 which was overexpressed in hepatocellular carcinoma, has been silenced with the consequent inhibition of the progression of tumors." (PMID 33868998, 2021). "Studies have found that increased CDCA5 interpretation is not only associated with increased HCC tumor diameter and microvascular invasion but may also be associated with hepatocellular carcinoma." (PMID 34651050, 2021). "In conclusion, our findings suggested that CDCA2, CDCA3, CDCA4, CDCA5, and CDCA8 might have potential diagnostic and prognostic values for hepatocellular carcinoma." (PMID 32913466, 2020). "CDCA3 and CDCA5 had been considered as potential oncogenes in hepatocellular carcinoma." (PMID 32913466, 2020). "In brief,CDCA5 is a promising novel prognostic factor for patients with hepatocellular carcinoma." (PMID 30497429, 2018). "In researches of hepatocellular carcinoma (HCC), CDCA5 was also found to be up-regulated in HCC cells, and related to poor prognosis." (PMID 34143800, 2021).
hepatocellular carcinoma (continued). "CDCA5 was transcribed by E2F1 in hepatocytes, promotes tumorigenesis by enhancing cell proliferation and inhibiting apoptosis of hepatocellular carcinoma through the AKT pathway, and was significantly related to the poor prognosis of liver cancer patients." (PMID 33190424, 2021). "CDCA5, transcribed by E2F1, potentiates the initiation of tumor by enhancing cell proliferation and inhibiting apoptosis via the AKT pathway in hepatocellular carcinoma." (PMID 32733928, 2020). "In Wurmbach's dataset 20, CDCA2, CDCA3, CDCA4, CDCA5 and CDCA8 were up-regulated in hepatocellular carcinoma (HCC), with fold changes of 1.813, 3.214, 1.832, 2.422 and 1.693, respectively." (PMID 32913466, 2020). "Moreover, CDCA5 was shown to be upregulated in hepatocellular carcinoma (HCC) tissues compared to paracancerous tissues, is negatively correlated with patient survival and associated with cell abnormalities via upregulation of the AKT pathway." (PMID 32716971, 2020). "In conclusion, we supposed that CDCA2, CDCA3, CDCA4, CDCA5 and CDCA8 might be oncogenes in hepatocellular carcinoma." (PMID 32913466, 2020).
gastric cancer (15 papers, 2018 to 2024). A primary or metastatic malignant neoplasm involving the stomach. "Cell division cycle associated 5 (CDCA5) is involved in the proliferation of gastric cancer cells, and its inhibition results in the downregulation of Cyclin E1 (CCNE1)." (PMID 36769170, 2023). "Cell division cycle associated 5 (CDCA5) is a core regulator of DNA repair and chromosome separation, and plays a carcinogenic role in gastric cancer, esophageal squamous cell carcinoma, and prostate cancer." (PMID 36685860, 2022). "As an example, in the TCGA gastric cancer cohort (STAD) for the gene CDCA5, we identified ten DREs associated with CDCA5 expression, with four of them > 240 kb away from the TSS of CDCA5." (PMID 29871649, 2018). "Multiple studies have revealed that CDCA5 is overexpressed in various cancers, such as lung cancer, oral squamous cell carcinoma, gastric cancer, and HCC." (PMID 35509067, 2022). "For digestive system cancer, CDCA5 is found to play crucial roles in the proliferation of gastric cancer cells." (PMID 32104702, 2020). "Curiously, gastric cancer showed inverse relationship for CDCA5, CRNN and DUOX1 on prognosis compared to other cancer types (red asterisks)." (PMID 31443700, 2019). "In addition, the ablation of CDCA5 inhibited gastric cancer cell proliferation via downregulating Cyclin E1 expression." (PMID 36741311, 2023). "Therefore, it has been suggested that CDCA5 is an upstream activator of Cyclin E1 for the development of gastric cancer." (PMID 36769170, 2023). "Recent studies have correlated the expression of CDCA5 with tumorigenesis and tissue invasion in several cancers, including oral squamous cell cancer, nonsmall cell lung cancer, urothelial cell carcinoma, and gastric cancer." (PMID 31708970, 2019). "Interestingly, gastric cancer showed inverse relationship for CDCA5, CRNN and DUOX1 on prognosis compared to other cancer types investigated." (PMID 31443700, 2019). "When CDCA5 was inhibited in gastric cancer cells, it suppressed their proliferation, demonstrating how CDCA5 promotes GC tumor progression." (PMID 35205681, 2022). "CDCA5 was coexpressed with CDK1 in gastric cancer, thereby affecting the normal cell cycle transition and thus leading to the proliferation of gastric cancer cells." (PMID 36004205, 2022). "Additionally, CDCA5 cooperates with cyclin-dependent kinase 1 (CDK1) to promote tumor cell proliferation, migration, and invasion abilities in gastric cancer." (PMID 38658931, 2024). "In gastric cancer tissues, CDK1 and CDCA5 expressions are correlated with each other, and this coexpression has been observed in MGC-803 cells, with the inhibition of one or both of these genes leading to suppression of invasion, migration, colony formation, and proliferation." (PMID 36769170, 2023).
lung carcinoma (15 papers, 2016 to 2022). "High CDCA5 expression in lung cancer showed a significant association with a poor prognosis for patients and also promoted cell proliferation." (PMID 26497678, 2016). "A study on lung carcinoma has shown high levels of CDCA5 and its association with poor prognosis." (PMID 31443700, 2019). "Furthermore, CDCA5 expression in peripheral T cells as well as tumor cells was associated with poor survival in lung cancer patients." (PMID 26497678, 2016). "Consistently, Ser209 phosphorylation on CDCA5 protein by ERK promoted growth or survival of lung cancer cells." (PMID 35509067, 2022). "Malignant progression was promoted by the upregulation of CDCA5 in urothelial carcinoma, lung cancer and oral squamous cell carcinoma, and predicted poor prognosis." (PMID 33190424, 2021). "In lung carcinoma, CDCA5 and its phosphorylation at Ser209 by ERK play an important role in lung cancer cell proliferation." (PMID 33937050, 2021). "Previous study shows that phosphorylation of CDCA5 at Ser209 by extracellular signal-regulated kinase (ERK) can inhibit the proliferation of lung cancer cells, which is inversed after the induction of exogenous expression of CDCA5." (PMID 32694239, 2020). "It has been proved that CDCA5 was significantly up-regulated in various human tumor tissues, including lung cancer, oral squamous cell carcinoma, urothelial cancer and gastric cancer." (PMID 32694239, 2020). "CDCA5 has been found to be overexpressed, and correlated with poor prognosis in several human cancers, including lung carcinomas, urothelial carcinoma, and oral squamous cell carcinoma." (PMID 30808873, 2019). "Furthermore, AURKB, CCNB2, CDC20, CDCA5, CDCA8, CENPF, and KNTC1 are were highly expressed in lung cancer tissues and were associated with poor prognosis." (PMID 35598017, 2022). "Moreover, CDCA5 phosphorylation and activation by mitogen-activated protein kinase are critical for human lung cancer." (PMID 35354488, 2022). "Previous studies indicated that CDCA5 knockdown could inhibit the growth of lung carcinoma and oral squamous cell carcinoma cell." (PMID 30808873, 2019). "Furthermore, a method for lung cancer and/or esophageal cancer treatment and prevention based on the overexpression of CDCA5 was developed and patented, proving the possible application of CDCA5 to cancer therapeutics." (PMID 29467944, 2018). "Furthermore, CDCA5 has been reported to be overexpressed in the majority of human lung cancers and urothelial cancers and to play a critical role in carcinogenesis." (PMID 26497678, 2016). "Although CDCA5 has been reported to have roles in cell cycle progression in a variety of immortalized cell lines, through its interaction with cohesin on chromatin, there is only one report that has investigated its possible role in carcinogenesis, in lung cancer." (PMID 26497678, 2016). "Their data suggested that transactivation of CDCA5 and its phosphorylation at Ser209 by ERK played an important role in lung cancer proliferation, and that the selective suppression of the ERK-CDCA5 pathway could be a promising strategy for cancer therapy." (PMID 34143800, 2021). "Up to now, there is no direct evidence that CDCA5 relates to the initiation and development of any subtype of lung cancer." (PMID 32149105, 2020).
bladder cancer (14 papers, 2019 to 2025). "The results showed that the high expression of S100A8 and CDCA5 in bladder cancer was associated with DSS Significantly correlated with poor prognosis of OS (HR >1, P <0." (PMID 39895787, 2025). "However, a previous study conducted on bladder cancer showed similar association between CDCA5 and PI3K/AKT/mTOR pathway, which supports our hypothesis." (PMID 36428736, 2022). "CDCA5 promotes the progression of bladder cancer by dysregulating mitochondria-mediated apoptosis, cell cycle regulation, and activation of the PI3k/AKT/mTOR pathway." (PMID 35354488, 2022). "For BCa, CDCA5 expression was higher in bladder cancer tissues than in matched adjacent normal tissues (P<0.05)." (PMID 32201512, 2020). "CDCA5 was overexpressed in bladder cancer tissues and activated PI3K/AKT/mTOR pathway." (PMID 35509067, 2022). "Among them, TOP2A, CDC20, CDCA5 and UBE2C all act as oncogenes in bladder cancer and promote tumor progression." (PMID 36932399, 2023).
prostate carcinoma (12 papers, 2020 to 2024). A carcinoma that arises from epithelial cells of the prostate gland. "The RNA sequencing data showed that genes coding for the cell division cycle associated protein (CDCA) family that contains CDCA1 to CDCA5 are upregulated in prostate cancer cell lines with different increasing levels." (PMID 32509575, 2020). "Recent research illustrated that CDCA5 activated prostate cancer and colorectal cancer cell proliferation via ERK signaling pathway." (PMID 36741311, 2023). "Ji J and his colleagues found that MAPK/ERK pathway might be the downstream signal pathway of CDCA5 in prostate cancer." (PMID 38658931, 2024). "The degradation of CDCA5 also inhibits prostate cancer progression." (PMID 36741311, 2023). "Moreover, CDCA5 is also differentially expressed in patients with localized and locally advanced prostate cancer." (PMID 32104702, 2020). "CDCA5 has been ascertained in multiple cancers and participates in the PI3K/AKT pathway to drive breast cancer development, as well as promote prostate cancer progression via effects on the ERK signaling pathway." (PMID 38181024, 2024). "CDC25C, CDCA5, TOP2A, and CENPU, genes whose expression levels were strongly correlated to CENPA expression in prostate cancer tissue, were all notably down-regulated with CENPA depletion, as well as bound by CENPA." (PMID 32371391, 2020).
esophageal squamous cell carcinoma (9 papers, 2020 to 2024). Esophageal squamous cell carcinoma (ESCC) is a type of esophageal carcinoma (EC) that can affect any part of the esophagus, but is usually located in the upper or middle third. "Given that CDCA5 is reported to be associated with chemosensitivity in esophageal squamous cell carcinoma, we thus examined the influence of CDCA5 to sunitinib treatment." (PMID 38658931, 2024). "Additionally, CDCA5 depletion inhibits the proliferation and metastasis in esophageal squamous cell carcinoma." (PMID 38658931, 2024). "Besides, CDCA5 can also be used as a potential therapeutic target for esophageal squamous cell carcinoma." (PMID 33190424, 2021). "Additionally, CDCA5 aids in the development of esophageal squamous cell carcinoma and may be an important target for esophageal squamous cell carcinoma immunotherapy." (PMID 35354488, 2022). "CDCA5 could promote proliferation, migration, invasion, apoptosis resistance and decrease chemosensitivity to cisplatin in esophageal squamous cell carcinoma (ESCC) cells." (PMID 32716971, 2020).
oral squamous cell carcinoma (8 papers, 2016 to 2022). "CDCA5 expression is elevated and is associated with a poor prognosis in several human cancers, such as urothelial carcinoma and oral squamous cell carcinoma." (PMID 33937050, 2021).
liver cancer (7 papers, 2018 to 2026). An epithelial or non-epithelial malignant neoplasm that arises from the liver. "Similarly, high expression of CDCA5 were associated with poor prognosis of breast, lung and liver cancers." (PMID 31443700, 2019). "It was also found that CDCA5 overexpression may be associated with liver cancer cells." (PMID 30497429, 2018). "The effect of CDCA5 on the proliferation of liver cancer cells was analyzed using in vitro and in vivo assays." (PMID 30497429, 2018). "Knockdown of CDCA5, another regulatory subunit of cohesin, can induce liver cancer." (PMID 35646080, 2022). "Principally, CDCA5 (AUC = 0.978) and CDC20 (AUC = 0.957) showed excellent diagnostic specificity and sensitivity and could be considered key oncogenic genes in liver cancer." (PMID 36685860, 2022). "CDCA5 is highly expressed in NSCLC and liver cancer and is associated with a poor prognosis." (PMID 32528520, 2020).
lung adenocarcinoma (7 papers, 2013 to 2024). A carcinoma that arises from the lung and is characterized by the presence of malignant glandular epithelial cells. "Another gene of interest to us is CDCA5 which has also been linked to cell cycle progression and its overexpression in lung adenocarcinoma leading to tumour progression." (PMID 32564237, 2020). "For CDCA5, the fold changes in Garber Lung's dataset were shown to be 7.928, 5.343, and 3.557 in large-cell LC, SCC, and lung adenocarcinoma in comparison with the common tissues, respectively." (PMID 32104702, 2020).
colorectal cancer (6 papers, 2019 to 2024). A primary or metastatic malignant neoplasm that affects the colon or rectum. "For example, there have been reports of the promotion of colorectal cancer progression by cell division cycle-associated 5 (CDCA5) and the functional role of E26 transformation-specific (ETS) variant 4 (ETV4) in pancreatic cancer." (PMID 33519944, 2021). "The TISCH study proved that CDCA5 was moderately expressed in immune cells and had a strong association with proliferating T cells, indicating that CDCA5 was implicated in the immune regulatory network by enhancing immune activation in colorectal cancer." (PMID 38213717, 2024). "Then we focused on colorectal cancer to learn more about the relationship between CDCA5 expression and TME." (PMID 38213717, 2024). "Two datasets of colorectal cancer (CRC GSE136394 and CRC GSE139555) from TISCH were analyzed to investigate the correlation between CDCA5 expression and tumor microenvironment (TME)." (PMID 38213717, 2024). "Functional significance of CDCA5 in colorectal cancer (CRC), however, has not been investigated." (PMID 30808873, 2019).
urothelial carcinoma (6 papers, 2018 to 2022). A malignant neoplasm derived from the transitional epithelium of the urinary tract (urinary bladder, ureter, urethra, or renal pelvis). "Although an association between CDCA5 and microvascular invasion in urothelial carcinoma has been shown, this is the first study reporting this relationship in HCC." (PMID 30497429, 2018). "Although there was a study that showed that CDCA5 overexpression is associated with advanced clinical features and poor prognosis of urothelial carcinoma, the underlying mechanisms of how CDCA5 promotes the tumorigenicity of BC remain unclear." (PMID 32201512, 2020).
ovarian carcinoma (5 papers, 2019 to 2025). A malignant neoplasm originating from the surface ovarian epithelium. "Nevertheless, the involvement of CDCA5 in ovarian cancer (OC), a highly aggressive form of cancer, and the underlying mechanism of metastasis remain inadequately investigated." (PMID 38539247, 2024). "It was found that CDCA5 plays a consistent pro-oncogenic role across different subtypes of ovarian cancer cell lines." (PMID 38539247, 2024). "Univariate and multivariate analyses of the correlation of CDCA5, FOXM1, KIF15, MCM2, and ZWINT expression with overall survival (OS) among epithelial ovarian cancer patients." (PMID 31708970, 2019).
Cirrhosis (3 papers, 2019 to 2024). A chronic disorder of the liver in which liver tissue becomes scarred and is partially replaced by regenerative nodules and fibrotic tissue resulting in loss of liver function. "PRC1, RACGAP1, and CDCA5 were identified as the crucial genes in the pathological progression from cirrhosis to HCC, and their hypomethylation may drive the high expression of these genes." (PMID 33505422, 2020).
breast tumor (2 papers, 2022 to 2024). "The activation of CDCA5 has been reported to induce breast tumor progression via PI3K-AKT-mTOR signaling pathway." (PMID 38658931, 2024). "CDCA5 expression was increased in breast tumor tissues than normal breast tissues in TCGA." (PMID 35509067, 2022).